GGT2P (gamma-glutamyltransferase 2, pseudogene)
Description:
[Isoform 1]: Lacks catalytic activity due to its inability to undergo the autocatalytic cleavage needed to produce a mature, enzymatically active heterodimer. [Isoform 2]: Lacks catalytic activity due to its inability to undergo the autocatalytic cleavage needed to produce a mature, enzymatically active heterodimer. [Isoform 3]: Lacks catalytic activity due to its inability to undergo the autocatalytic cleavage needed to produce a mature, enzymatically active heterodimer.
Synonyms: formerly GGT; GGT2
Gene: Transcribed unprocessed pseudogene on chromosome 22 (21,207,973 to 21,225,554, reverse strand). Ensembl gene ENSG00000133475.
Subcellular location: Cytoplasm, perinuclear region; Endoplasmic reticulum
Genetic constraint (gnomAD): Loss-of-function variants: 4 observed, 7.08 expected, observed/expected ratio (o/e) 0.57, 90% interval 0.28 to 1.29. That is too few expected variants to judge how well the gene tolerates losing a copy. Missense variants: 22 observed, 76.8 expected, observed/expected ratio (o/e) 0.29, 90% interval 0.2 to 0.41. Synonymous variants: 12 observed, 32.93 expected, observed/expected ratio (o/e) 0.36, 90% interval 0.23 to 0.59.
Diseases named in the same sentence as GGT2P in open-access papers:
GGT2P is named in the same sentence as 7 diseases in open-access papers, as found by Europe PMC text mining. Sharing a sentence is not in itself a finding about the gene and the disease. The quoted sentences say what the papers report.
cancer (2 papers, 2024 to 2025). A tumor composed of atypical neoplastic, often pleomorphic cells that invade other tissues. "Among the recurrent and predicted deleterious variants, only the GGT2 p.R535W has been previously reported in cancer (COSM3766685)." (PMID 39456581, 2024).
GGT2P also shares sentences with these, for which no sentence is quoted: tumor (2 papers); glioblastoma (1); infection (1); liver disease (1); progressive familial intrahepatic cholestasis (1); prostate carcinoma (1).